RN7SL489P (RNA, 7SL, cytoplasmic 489, pseudogene)
Gene: Miscellaneous RNA gene on chromosome 15 (75,268,430 to 75,268,652, forward strand). Ensembl gene ENSG00000277295.
Homologues: Orthologues: macaque Metazoa_SRP (75% identical), macaque Metazoa_SRP (48% identical), macaque Metazoa_SRP (47% identical), macaque Metazoa_SRP (46% identical), macaque Metazoa_SRP (45% identical), macaque Metazoa_SRP (43% identical), macaque Metazoa_SRP (34% identical), macaque Metazoa_SRP (33% identical), macaque Metazoa_SRP (32% identical), macaque Metazoa_SRP (19% identical), macaque Metazoa_SRP (18% identical), macaque Metazoa_SRP (17% identical), and 2 more. Paralogues in human: RN7SL327P (100% identical), RN7SL429P (100% identical), RN7SL853P (100% identical), RN7SL241P (86% identical), RN7SL214P (83% identical), RN7SL417P (79% identical), RN7SL319P (78% identical), RN7SL469P (76% identical), RN7SL673P (76% identical), RN7SL495P (76% identical), RN7SL628P (76% identical), RN7SL719P (76% identical), and 709 more.